GNAS-AS1 (GNAS antisense RNA 1)
Synonyms: SANG; NESP-AS; NESPAS; GNAS1AS; NCRNA00075; GNAS-AS; GNASAS
Gene: Long non-coding RNA gene on chromosome 20 (58,818,893 to 58,855,296, reverse strand). Ensembl gene ENSG00000235590.
Diseases named in the same sentence as GNAS-AS1 in open-access papers:
GNAS-AS1 is named in the same sentence as 19 diseases in open-access papers, as found by Europe PMC text mining. Sharing a sentence is not in itself a finding about the gene and the disease. The quoted sentences say what the papers report.
lung carcinoma (1 paper, 2019). "Intriguingly, GNAS-AS1 downregulation by methylation has been associated to colorectal tumorigenesis as well as to lung cancer susceptibility." (PMID 31337866, 2019).
pseudohypoparathyroidism (1 paper, 2024). "Despite the thorough analysis, no known pathogenic variants were found in genes typically associated with Fahr’s syndrome (e.g., XRP1, PDGFRB, JAM2, PDGFB, SLC20A2, or MYORG) or pseudohypoparathyroidism (e.g., GNAS, STX16, or GNASAS1)." (PMID 39519162, 2024).
tumor (2 papers, 2022 to 2024). "GNAS-AS1, also known as GNAS Antisense RNA 1 as one of the alternative transcripts of human GNAS locus localized on chromosome 20q13.3, has often been disclosed as the lncRNA responsible for tumor initiation and development in various cancers." (PMID 38668383, 2024).
GNAS-AS1 also shares sentences with these, for which no sentence is quoted: hepatocellular carcinoma (2 papers); asthma (1); breast carcinoma (1); cancer (1); diabetes (1); follicular adenoma (1); glioblastoma (1); Infertility (1); male infertility (1); metabolic disorders (1); myocardial infarction (1); non-small cell lung carcinoma (1); ovarian teratoma (1); pancreatic cancer (1); pseudohypoparathyroidism type 1B (1); transient neonatal diabetes mellitus (1).